DKK1 (dickkopf Wnt signaling pathway inhibitor 1)
Diseases named in the same sentence as DKK1 in open-access papers (continued):
Sharing a sentence is not in itself a finding about the gene and the disease.
breast carcinoma (continued). "Similarly, in syngeneic murine mammary carcinoma cells, weakly-metastatic 4TO7 cells expressed much less DKK1 compared to highly metastatic 4T1 cells, although 4TO7 exhibited mesenchymal-like morphology and increased migrative/invasive capacity compared to epithelial-like 4T1 cells." (PMID 35296660, 2022). "Interestingly, the mechanism of increasing PTEN transcription may be the same as the enhanced DKK-1 expression in breast cancer, where CBX7 recruits p300 independently of PRC1 to the promoter region to participate in epigenetic changes." (PMID 34659360, 2021). "However, the relationship between MMP7 and DKK1 remain elusive in breast cancer." (PMID 31285694, 2019). "However, the mechanism of DKK1 inhibits breast cancer migration and invasion was still unclear." (PMID 31285694, 2019). "Therefore, we then investigate whether DKK1 regulates the expression of MMP7 in breast cancer cells." (PMID 31285694, 2019). "Therefore, we asked whether DKK1 suppressed cell migration and invasion by regulating β-catenin expression in breast cancer cells." (PMID 31285694, 2019). "However, the mechanism of DKK1 inhibits breast cancer metastasis was still unclear." (PMID 31285694, 2019). "Therefore, our results could be explained by the fact that breast cancer cells produce high amounts of DKK1 and it might be possible that DKK1 levels differ in patients depending on disease status." (PMID 30227689, 2018). "However, overexpression of DKK1 has been observed in various malignant tumors and is also correlated with adverse prognosis in patients with multiple myeloma, hepatoblastoma, Wilm’s tumor, lung cancer, and breast cancer." (PMID 29720122, 2018). "However, to our knowledge the expression of DKK-1 in breast cancer is little known." (PMID 25116444, 2014). "The data suggest that serum DKK-1 may be a useful molecular marker in breast cancer." (PMID 25116444, 2014). "Indeed, DKK1 as well as other Wnt antagonists have been shown to inhibit breast cancer progression." (PMID 24898756, 2014). "To test this hypothesis, we investigated the expression of DKK1 and beta-catenin in tumor specimens from 85 patients with breast cancer and the correlation between DKK1 and beta-catenin together with other clinical pathological features of prognosis in this study." (PMID 22649545, 2012). "Indeed, DKK1 is a secreted tumor suppressor in breast cancer." (PMID 21952072, 2011). "Indeed, a role for DKK1 overexpression in cancer, including hepatobastomas and breast cancer bone metastasis, aggressive tumors, epithelial-mesenchymal transition and proliferation, has been previously suggested, although its precise mechanism of action has not yet been elucidated." (PMID 19732436, 2009). "Interestingly, DKK1 was preferentially expressed in oestrogen and progesterone receptor-negative tumours (ER−/PR−; P=0.005) and in tumours from women with a family history of breast cancer (P=0.024)." (PMID 17245340, 2007). "A prostate cancer cell line, PC3, and a breast cancer cell line, MDA-MB-231 exhibited high levels of DKK1 expression, confirmed by high DKK1 protein levels in their culture media." (PMID 40025612, 2025). "In breast cancer, MEX3A was shown to bind the 3′UTR of DKK1 mRNA and repress its translation via Dcp-containing P-body dependent decay." (PMID 41516083, 2025). "Further subtype analysis based on established breast cancer CAF classification, showed DKK1 expression in ACTA2+COL1a1highPDGFRα+ myofibroblasts (myCAF)." (PMID 39885132, 2025). "Treatment with the humanized immunoglobulin G4 (IgG4) anti-DKK1 antibody, DKN-01, inhibited tumor growth in a natural killer (NK) cell-dependent manner in both a metastatic breast cancer model and a prostate cancer model." (PMID 40394415, 2025).
breast carcinoma (continued). "In addition, a murine model of breast cancer had unveiled that DKK1 overexpression markedly enhanced bone metastasis and osteolysis, concurrently upregulated tumor proliferation within metastatic sites, and the knockdown of DKK1 could mitigate bone metastasis." (PMID 38744806, 2024). "[Δ: Percentage of Dkk1-IRS reduction, IRS1: Dkk1-IRS in core needle biopsy tissue, IRS2: Dkk1-IRS in mammary carcinoma tissue]." (PMID 38254908, 2024). "Mechanistically, CTTN downregulates DKK-1, a Wnt antagonist, in HER2+ breast cancer, resulting in activation of the Wnt signaling pathway and expansion of the number of CSCs, as well as resistance to trastuzumab." (PMID 36831511, 2023). "By joint analysis of gene expression data from previous studies, we constructed interrelationships of mainly CRHBP, ICAM1, PLAGL1, DNMT1, CNTLN, DKK1, and EGR2 with preterm birth, infant disease, and breast cancer." (PMID 36788602, 2023). "The significant associations observed between DARPP-32 and its downstream targets DKK1 and GRB7 and patient survival, underscore their importance in breast cancer." (PMID 38036593, 2023). "KEGG pathway analysis showed that genes in the DKK1 PPI were mainly enriched in the WNT signaling pathway, basal cell carcinoma, breast cancer, gastric cancer, and hepatocellular carcinoma pathways." (PMID 34899842, 2021). "In breast cancer, CBX7 increases Dickkopf-1 (DKK-1, a Wnt antagonist) gene transcription, thus indirectly affecting the Wnt signaling pathway." (PMID 34659360, 2021). "BMP4 and C3 were significantly expressed in normal tissue as compared to cancerous breast cancer tissues whereas CXCL13 and DKK1 is observed to be expressed in breast cancer tissue as compared to normal breast tissue." (PMID 34754042, 2021). "Collectively, these results show that PRMT5 controls breast cancer cell growth through epigenetic silencing of WNT/β‐CATENIN pathway antagonists, DKK1 and DKK3, resulting in up‐regulation of WNT/β‐CATENIN proliferative signalling." (PMID 33462997, 2021). "Our PPI analysis and the pathway enrichment analysis showed that the genes interacting with DKK1 were mainly involved in the WNT signaling pathway, basal cell carcinoma, breast cancer, gastric cancer, and liver cancer." (PMID 34899842, 2021). "DKK1 had decreased expression in both gastric cancer (GC) and colorectal cancer (CRC), but increased expression in breast cancer (BRCA) and non-small cell lung cancer (NSCLC)." (PMID 34899842, 2021). "Western blot and real time PCR was used to detect the expression of DKK1, β-catenin and MMP7 in breast cancer cells." (PMID 31285694, 2019). "MYC was found to repress the WNT inhibitors DKK1 and SFRP1, leading to the activation of the WNT pathway in breast cancer cell lines." (PMID 31623618, 2019). "It has been proven that c-MYC transforms human mammary epithelial cells through the repression of the Wnt inhibitors DKK1 and SFRP1 in breast cancer cell lines." (PMID 30866868, 2019). "Overexpression of DKK1 represses MMP7 expression and inhibits migration and invasion of breast cancer cells." (PMID 31285694, 2019). "The levels of DKK1 and SFRP1 were also significantly decreased by exercise training in breast cancer survivors (all p < 0.01)." (PMID 28178355, 2017). "We demonstrated that long-term exercise decreases the serum levels of DKK1 and SFRP1 and improves physical fitness and biomarker levels related to metabolic conditions in breast cancer survivors." (PMID 28178355, 2017). "Endocrine-sensitive or -resistant breast cancer cell lines were used to examine the expression of the stem cell gene SOX2, and the Wnt effector genes AXIN2 and DKK1 using quantitative PCR analysis." (PMID 28929082, 2017). "In this study, we detected reduced serum levels of DKK1 and SFRP1 in breast cancer survivors following a long-term (12-week) exercise program." (PMID 28178355, 2017).
breast carcinoma (continued). "Osteolytic cancer cells, such as breast cancer cells, overexpress Sclerostin (SOST) or Dickkopf1 (Dkk1), which play inhibiting roles in the Wnt signaling pathway, leading to downregulation of cell proliferation and differentiation." (PMID 28303941, 2017). "In human breast carcinoma, high levels of PTOV1 expression correlated with high levels of nuclear β-catenin and low levels of DKK1." (PMID 28029646, 2017). "In breast cancer cells, BMI1 can repress the dickkopf WNT signaling pathway inhibitor 1 and induce c-Myc expression to further activate BMI1 expression." (PMID 28914785, 2017). "Several Wnt/β-catenin antagonists were epigenetically repressed in breast cancer, including WIF1, SFRP1, SFRP2, SFRP5, DKK1, and DKK3." (PMID 28467796, 2017). "Serum DKK1 was found to be elevated in cancer types such as HCC, breast cancer with bone metastasis and cervical cancer." (PMID 26799283, 2016). "Antibodies that neutralize DKK1 or sclerostin are in trials and may have beneficial effects to relieve the suppression of bone formation caused by these WNT inhibitors, which can be made by breast cancer cells and myeloma as well as by bone (osteocytes in the case of sclerostin)." (PMID 25757219, 2014). "As predicted by our results in WT6 and WT10 cells, knockdown of RBM47 in two additional breast cancer cell lines expressing high levels of endogenous RBM47, SKBR3 and ZR-75-30, reduced DKK1 mRNA levels." (PMID 24898756, 2014). "Breast cancer cells also secrete activin A (a member of transforming growth factor (TGF)-β), noggin (a bone morphogenetic protein (BMP) antagonist) and dikkopf-1 (DKK-1; a wingless (Wnt) protein antagonist), all of them inhibiting osteoblast differentiation." (PMID 26237142, 2013). "As DKK1 was recently shown to be epigenetically silenced in CRC, we also analysed expression of DKK1 in the breast cancer cells." (PMID 18283316, 2008). "A prior study identified that DKK1 could induce downregulation of NKG2D and DNAM-1 ligands in a metastatic latency breast cancer model." (PMID 39885132, 2025). "Intriguingly, deletion of CAF-derived DKK1 also limits breast cancer progression, without affecting its levels in circulation, and regardless of DKK1 expression in the tumor cells." (PMID 39885132, 2025). "Monitoring DKK1 levels in circulation and in the TME, and DKK1 neutralization should be considered to improve the therapeutic response of NK-based strategies and/or the limited efficacy of immunotherapies in breast cancer." (PMID 39885132, 2025). "Interestingly, in studies of breast cancer, LGR4 has been found to promote DKK1 secretion, which promotes breast cancer bone metastasis." (PMID 40469438, 2025). "Collectively, these findings suggest that in human breast cancer, DKK1 directly suppresses NK cells, rather than modulating the tumor cells." (PMID 39885132, 2025). "As expected, DKK1 staining was observed in TNBC and HER2+ cancer epithelial cells, identified by the expression of the pan-cytokeratin (PanCK) marker, but very limited expression was found in ER+ breast cancer." (PMID 39885132, 2025). "Collectively, these findings suggest that in human breast cancer, DKK1 directly suppresses NK cells, rather than exhibiting direct effects on tumor cells." (PMID 38659818, 2024). "Similarly, DKK1 neutralization significantly reduced the growth of the luminal B, ER/PR+, hormone-sensitive EO771 breast cancer cell line." (PMID 38659818, 2024). "If, as our data suggest, DKK1 expression can be modulated by a SERM and the glycoprotein contributes to metastatic progression, then this study has revealed a new therapeutic axis that can be exploited to treat endocrine-resistant ESR1 mutant breast cancer." (PMID 38978585, 2024). "Intriguingly, specific deletion of CAF-derived DKK1 also limits breast cancer progression, regardless of its elevated levels in circulation and in the bone." (PMID 38659818, 2024).
breast carcinoma (continued). "Similarly, an insignificant impact on canonical WNT was detected in breast cancer MDA-MB-231 cells and prostate cancer PC3 cells, which produce large amounts of DKK-1." (PMID 38067123, 2023). "Consistently, it was observed that DKK1 selectively increased the metastatic burden of breast cancer without impacting primary tumor growth." (PMID 35296660, 2022). "DTCs can escape NK cell-mediated elimination through the expression of the wingless-related integration site (WNT) antagonist dickkopf WNT signaling pathway inhibitor 1 (DKK1), as demonstrated in lung adenocarcinoma and HER2-positive breast cancer mouse models." (PMID 35837334, 2022). "For example, higher VD levels were associated with lower methylation of Wnt Family Member 5A (WNT5A) and dickkopf 1 (DKK1) genes in colorectal cancer patients and higher methylation of Retinoid X Receptor Alpha (RXRA) and NAD Synthetase 1 (NADSYN1) genes in breast cancer patients." (PMID 36430854, 2022). "However, DKK1 inhibits lung metastasis through suppressing WNT/Ca2+-CaMKII-NF-κB signaling, indicating a dual role of DKK1 in the metastasis of breast cancer." (PMID 35800432, 2022). "Hence, these data suggest that BCSC-derived DKK1 shrunk the CSC pool and reduced the tumor-initiating capacity in breast cancer cells." (PMID 35296660, 2022). "By screening the function of the BCSC-derived secretome in the regulation of cancer cell phenotypic plasticity, DKK1 was identified as a pivotal molecule that autonomously diminishes the CSC population and subsequently promotes breast cancer metastatic colonization." (PMID 35296660, 2022). "For this, we induced EMT in BT474 (HER2-high breast cancer cells) by treating the cells with an EMT-inducing supplement cocktail (containing Wnt-5a, TGF-β1, anti-human E-Cadherin antibody, anti-human sFRP1 antibody, and anti-human Dkk1 antibody) for 15 days." (PMID 34575017, 2021). "Furthermore, DKK1 and DKK3 promoter hypermethylation have been documented in many primary breast cancer tumours." (PMID 33462997, 2021). "Interestingly, the MSC-induced pro-tumorigenic effect seems to be regulated by Wnt/β-catenin signaling in breast cancer, whereas the inhibition of tumor proliferation occurs by MSC-induced secretion of DKK-1, an inhibitor of the same pathway." (PMID 33575478, 2021). "Increased mRNA expression of AXIN2 (1.9-fold), LEF1 (2.3-fold), and DKK1 (3.2-fold) was also observed in T47D cells expressing GFP-INPP4B, demonstrating that INPP4B enhances Wnt/β-catenin signaling in PIK3CA-mutant ER+ breast cancer cells." (PMID 34035258, 2021). "Three of the top four genes enriched in PRC2+-CGI EMT pathway had not been functionally implicated in the EMT phenotype in breast cancer (SERPINE2, DKK1, MATN3)." (PMID 33931649, 2021). "On the other hand, in breast cancer patients with a low DKK1 expression, activation of the non-canonical Wnt signaling pathway induced an elevated expression of TGF-β and PGE2, thus promoting lung metastasis." (PMID 31698687, 2019). "Moreover, it is suggested that the levels of endogenous negative regulators of Wnt/β-catenin including DKK1 and secreted frizzled-related protein-1 may be potentially employed as biomarkers for evaluating the beneficial effects of exercise on the metabolism and prognosis of breast cancer patients." (PMID 31511432, 2019). "Our study suggested that elevated serum DKK1 level could be a marker for the presence of bone metastases in NSCLC, as well as breast cancer, multiple myeloma and prostate cancer." (PMID 29108326, 2017). "Spearman’s rank order correlation coefficients of relative gene expression values (fold change) for AXIN2, DKK1, and SOX2 versus IC50 value of the WNT inhibitors LGK974 and IWP-2 in MCF-7 parental and endocrine therapy-resistant breast cancer cell lines (n = 14)." (PMID 28929082, 2017).
breast carcinoma (continued). "Moreover, DKK1, a direct downstream target of the Wnt/β-catenin pathway, was found overexpressed in TNBC breast cancer as a consequence of the hyperactivation of Wnt/β-catenin signaling, also in association with poor outcome." (PMID 27420097, 2016). "Methylation of DKK1 and DKK3 promoters has been reported in breast cancers." (PMID 27420097, 2016). "Among them, DKK1 (dickkopf WNT signaling pathway inhibitor 1) is found to be regulated by NBAT1 in a PRC2 dependent manner, and is responsible for NBAT1's effects in inhibiting migration and invasion of breast cancer cells." (PMID 26378045, 2015). "The most upregulated proteins by SBP1 induction included DKK1 that inhibits WNT pathway, DHCR7 that controls cholesterol and Vitamin D synthesis, ANXA4 that inhibits NFkB pathway and IL-8, and AGPAT5 that inhibits breast cancer cell proliferation." (PMID 25974208, 2015). "Several studies have demonstrated that DKK1, an inhibitor of WNT signaling pathway, could inhibit the migration and invasion of breast cancer." (PMID 26378045, 2015). "Addition of IWP-2 reduced DKK1 and AXIN2 expression in tamoxifen resistant breast cancer cells." (PMID 24178749, 2014). "The fact that RBM47 was able to increase DKK1 secretion therefore suggested that RBM47 may also inhibit Wnt signaling and consequently reduce the tumorigenic fitness of metastatic breast cancer cells." (PMID 24898756, 2014). "In this study, we identified an increased expression of DKK-1 in hormone-negative and highly osteotropic breast cancer cell lines." (PMID 24528599, 2014). "Here we identified DKK-1 as a novel target of the mevalonate pathway in estrogen receptor (ER)-negative breast cancer that can be modulated by BPs and statins via inhibiting of geranylgeranylation." (PMID 24528599, 2014). "Although DKK1 mRNA expression was detected in receptor-positive or HER2-positive breast cancer cells we studied, no such protein expression was found in these cells." (PMID 22649545, 2012). "In the BANs generated, DKK1 is a highly interconnected node in the colon cancer cell lines, UGT1A family members formed a network of genes differentially expressed in breast cancer, and EEF1A1 was commonly overexpressed in pancreatic cancer, leukemia and osteosarcoma." (PMID 19732436, 2009). "In addition to PC3 prostate cancer cell, cancer cell lines related to breast cancer (SKBR3), gastric adenocarcinoma (NCI-N87) and colon cancer (Colo-205) were selected for evaluation of the DKK1 antibodies in the cytotoxicity assay to strengthen the clinical translational value." (PMID 40394415, 2025). "However, the inhibitor DKK1 efficiently inhibited both ER+ve and ER-ve breast cancer but not normal mammosphere formation, suggesting that the Wnt pathway is aberrantly activated in breast cancer mammospheres." (PMID 23861811, 2013). "Interestingly, serum Dkk-1 levels in women with breast cancer and metastases at non-bone sites were lower than values found in patients with bone metastases and were not different from those of healthy women." (PMID 17876334, 2007). "Finally, we observed coexpression of DKK1 and HER-2/neu in breast cancer cells in only one out of the 21 DKK1+ tumours (data not shown)." (PMID 17245340, 2007). "Median serum Dkk-1 levels were significantly higher in women with breast cancer and bone metastases compared to women with breast cancer in complete remission (P=0.016), women with breast cancer and metastases at non-bone sites (P<0.0001) and healthy women (P=0.047)." (PMID 17876334, 2007). "In breast cancer, due to the lack of CBX7, the transcriptional activation complex p300/CBP dissociates from the promoter region of DKK-1 and restarts HDAC-mediated DKK-1 gene silencing." (PMID 34659360, 2021).
breast carcinoma (continued). "As a proof of principle that DKK-1 is a clinically relevant target of the mevalonate pathway, we assessed serum DKK-1 levels in patients with ER-negative and nonmetastatic breast cancer who received either 4 mg zoledronic acid (n = 6) or placebo (n = 3) every 3 months." (PMID 24528599, 2014). "In addition, there is a strong and significant quantitative difference in DKK1 expression between A-ROD–positive and A-ROD–negative samples, and a significant correlation between DKK1 and A-ROD expression across a panel of both ERa-positive and ERa-negative breast cancer samples." (PMID 29691407, 2018).